DACH1 (dachshund family transcription factor 1)
Diseases named in the same sentence as DACH1 in open-access papers (continued):
Sharing a sentence is not in itself a finding about the gene and the disease.
tumor (continued). "Conversely, the human Dachshund homologue 1 (DACH1) is recognized as a tumor suppressor which retards the progression of various cancers." (PMID 29636079, 2018). "Taken together, these results suggest that DACH1 is a tumor-suppressor in the growth and progression of LSCC." (PMID 30261897, 2018). "Decreased expression of DACH1 was found in the tumors upraglottic tumor, lymph node metastases, T3–4 stage and advanced clinical stage." (PMID 30261897, 2018). "A549 cells with sustained DACH1 expression possessed less tumorigenic potential and slower tumor growth rate than A549-vector and A549-ΔDS cells in vivo." (PMID 29636079, 2018). "It is reported that the LC invasion and tumor growth can be inhibited by DACH1 through suppressing the CXCL5 signaling." (PMID 30364292, 2018). "The results implicated that DACH1 suppressed the expression of some CSCs and EMT markers and serves as a potent anti-tumor factor in xenograft tumors." (PMID 28659634, 2017). "Up-regulation of DACH1 significantly reduced the volume of tumors by ∼90% and slowed down tumor growth." (PMID 28659634, 2017). "Herein, we initially studied the role of the DACH1 gene in adult kidney diseases outside of the tumor field." (PMID 27888806, 2016). "DACH1 is a tumor suppressor, while SIX/EYA promote malignancy, so aberrations in these components of the RDGN signaling machinery enable cells to acquire oncogenic properties." (PMID 27203207, 2016). "Our results suggest that DACH1 acts as a tumor suppressor by targeting PRX3 functional target genes in malignant lung cells." (PMID 26810067, 2016). "Recently, DACH1 was shown to suppress the growth and invasion of tumor cells in a variety of researches." (PMID 26810067, 2016). "More important, lower DACH1 expression significantly correlated with tumor diameter and tumor invasion." (PMID 26810067, 2016). "Exploring the mechanism of DACH1 in human disease has, to date, mostly focused on its role in restricting tumor cell proliferation and inhibiting solid tumor migration and invasion due to DACH1 down-regulation in cancer tissues." (PMID 27888806, 2016). "As a transcription factor, DACH1 likely inhibits tumor growth and progression via transcriptional regulation of target gene expression." (PMID 26810067, 2016). "Suppression of cyclin D1 and cyclin A by DACH1 negatively regulates cell cycle progression and thereby blocks cellular proliferation and tumor growth in various cancers." (PMID 27203207, 2016). "Lower DACH1 expression significantly correlated with tumor diameter (*P = 0.043) and tumor invasion (*P = 0.045)." (PMID 26810067, 2016). "Recent genetic study indicated that another RDGN member DACH1 is a promising tumor suppressor and mechanism analysis demonstrated that DACH1 inhibited cancer proliferation and invasion." (PMID 27821176, 2016). "The next logical step would be to search for a compound that can induce the expression of DACH1 in tumor tissues." (PMID 27203207, 2016). "Imbalance between the tumor-restraining effect of DACH1 and the oncogenic functions of SIX/EYA accelerates cell cycle progression and attenuates apoptosis, creating a favorable environment for uncontrolled proliferation." (PMID 27203207, 2016). "DACH1 is expressed widely in normal adult tissues, which functions as a tumor suppressor in a variety of malignant tumors in previous studies." (PMID 26810067, 2016). "Because of the possible roles of DACH1 in regulation of transcription and tumor suppression, we were intrigued to discover a common 5′ CNV, which proved to be a trinucleotide GGC repeat encoding glycine." (PMID 25776071, 2015). "Clinically, a decreased expression of DACH1 in breast and endometrial cancer correlates with tumor progression, poor differentiation and predicts a short survival." (PMID 25788272, 2015).
tumor (continued). "Together, we provided an evidence that CXCL5 was a critical chemokine for DACH1-mediated repression of motility and tumor growth." (PMID 25788272, 2015). "Recent findings supported the role of DACH1 as a novel tumor suppresor in several kinds of human cancers." (PMID 25788272, 2015). "The results showed that expression of CXCL5 was high in the cytoplasm of tumor cells expressing control vector, but very weak in tumor cells expressing DACH1." (PMID 25788272, 2015). "DACH1 restrained proliferation, migration in vitro and repressed tumor growth and metastasis in vivo." (PMID 26682253, 2015). "DACH1 expression in tumor tissues was arbitrarily classified as high (IHC score ≥ 6) in 48 cases and low (IHC score < 6) in 47 HCC patients." (PMID 25940701, 2015). "Recently, DACH1 emerged as an important tumor suppressor gene and its frequent methylation in OSCC underscores the potential anti-cancer effects of epigenetic therapies via suppression of Wnt signaling." (PMID 25487617, 2015). "The cell fate determination factor Dachshund (DACH1) functions as a novel suppressor in the progression of various neoplasms." (PMID 25940701, 2015). "These functions of DACH1 have shed more light on the mechanism by which DACH1 acts as a tumour suppressor." (PMID 25775416, 2015). "As shown in, the dramatic decrease of tumor size was noticed in the animals inoculated with A549 cells expressing DACH1 compared with vector control." (PMID 25788272, 2015). "As to the clinical-pathological relevance of DACH1 in NSCLC, we observed that DACH1 abundance was inversely corelated with tumor stage, grade and metastasis, which is consistent with previous reports." (PMID 25788272, 2015). "In this study, we employed public microarray data analysis and tissue microarrays (TMAs) technologies and showed that DACH1 expression was reduced in HCC even at early stage and associated with the tumor progression." (PMID 25940701, 2015). "In order to further evaluate tumorigenecity in vivo, CAKI cells expressing DACH1 and the vector control were subcutaneously implanted to immunodeficient mice and the tumor growth was monitored twice a week." (PMID 25322986, 2014). "Of the three ER associated GATA3 targets identified above, BCL2 has the best characterized tumor-promoting activity, while DACH1 has been reported to function as both tumor promoter and tumor suppressor." (PMID 25410484, 2014). "Nuclear DACH1 expression was strongly increased in patients with ER-alpha positive tumours co-expressing PgR, and epithelial CK18/19 cytokeratins." (PMID 24392136, 2014). "As DACH1 suppresses GC growth both in vitro and in vivo, it suggests that DACH1 is a tumour suppressor in human GC." (PMID 24912879, 2014). "Dachshund (DACH1) network is a key signaling pathway for kidney development and has recently been identified as a tumor suppressor in several cancer types." (PMID 25322986, 2014). "Methylation of DACH1 correlated with reduced expression of DACH1 (P < 0.01), late tumour stage (stage III/IV) (P < 0.01) and lymph node metastasis (P < 0.05)." (PMID 24912879, 2014). "The predictive independence of DACH1 was tested using multivariate models (Cox regression) incorporating endocrine therapy, clinical stage, tumour size and NPI status." (PMID 24392136, 2014). "The growth curve revealed a dramatic decrease of tumor size in the CAKI group following DACH1 expression." (PMID 25322986, 2014). "DACH1 expression was significantly increased in tumours of low grade, good Nottingham Prognostic Index and candidacy for hormonal therapy." (PMID 24392136, 2014).
tumor (continued). "In the current study we found that moderate to high tumour nuclear DACH1 expression in the majority of cancer cells is compatible with functionally blocking PELP1 activity, reflected by its association with good prognosis." (PMID 24392136, 2014). "The upregulation of DACH1 in CRC is strongly correlated with increased tumor proliferation, invasion, and metastasis, suggesting that DACH1 may possess distinct biological functions and mechanisms within this particular cancer subtype." (PMID 40389405, 2025). "Additionally, transfection of HCT8 cells with specific shRNAs targeting USP7 or treatment of RKO cells with the USP7 inhibitor P5091 significantly inhibited tumor volume growth and weight, which was largely reversed in the context of DACH1 overexpression." (PMID 40389405, 2025). "Recent studies using organoid models have indicated that DACH1 may act as a tumor promoter in CRC by modulating BMP signaling pathways." (PMID 40389405, 2025). "Likewise, we detected reduced CEBPA and DACH1 staining in miR‐31‐overexpressing tumours, whereas increased CEBPA and DACH1 in mPTC/miR‐31−/− tumours." (PMID 38797942, 2024). "Notably, Dach1 (Dachshund homolog 1) is transcription factor and a putative tumor suppressor that suppresses breast cancer tumor growth, spread and stemness." (PMID 38581619, 2024). "The results of the immune infiltration analysis showed that patients in the DACH1 low expression group had higher immune scores and lower tumor purity, which suggested that DACH1 could be able to promote immune cell infiltration." (PMID 36959804, 2023). "However, after DACH1 down-regulation, temozolomide’s ability to prevent tumor migration was lost, and the cells even displayed a stronger capacity for invasion than in temozolomide-free conditions." (PMID 36959804, 2023). "The sensitivity of tumor cells to temozolomide was significantly reduced after DACH1 was silenced." (PMID 36959804, 2023). "Furthermore, DACH1 suppressed tumor growth and EMT of mouse BC models via blocking YB-1 and inhibited BC cell initiation by decreasing CD44 levels." (PMID 36750914, 2023). "Furthermore, DACH1 expression decreased significantly with increasing tumor grade, and it was also lower in patients with advanced age, IDH wild-type, and MGMT non-methylation." (PMID 36959804, 2023). "Finally, xenograft tumor assays were adopted to validate the effects of DACH1 on tumor growth and S100A8/A9 expression." (PMID 38093319, 2023). "An earlier study found that DACH1 is less expressed in EC than in normal endometrium, suggesting that DACH1 may play a tumor-suppressing role in EC." (PMID 36551694, 2022). "Studies revealed that miR-194-5p acts as a tumor promotor by targeting DACH1." (PMID 36539807, 2022). "Dach1(Dachshund homologue 1) is a tumor promoter that is highly expressed in all stages of CAC." (PMID 35565775, 2022). "Both TLE3 and the tumor suppressor DACH1 are negative regulators of Wnt signaling." (PMID 34795231, 2021). "Meanwhile, DACH1 expression was lower in tumor tissue than in normal lung tissue." (PMID 33435990, 2021). "As expected, given the marked difference in tumor mutation counts in both TCGA PCA and MCC, DACH1 wild-type patients had a median TMB of 6.02 and DACH1 mutated patients had a significantly higher median TMB of 24.0 (p-value = 4.29E-05) compared by the Wilcoxon rank sum test." (PMID 33378353, 2020). "Previous study showed that ectopic expression of DACH1 inhibited tumor growth." (PMID 31998654, 2019).
tumor (continued). "Increased DACH1 expression inhibited the volume of tumor by 85% and decelerated the tumor growth." (PMID 29636079, 2018). "Meanwhile, DACH1 was negatively correlated with tumor stage in early stage of ADC (p = 0.0001)." (PMID 29636079, 2018). "DACH1 accounts for the carcinogenesis of various tumor types, including human breast cancer." (PMID 28659634, 2017). "Several lines of evidence indicated that DACH1 expression correlated with tumor differentiation." (PMID 28659634, 2017). "Furthermore, hypermethylation of DACH1 promoter region itself led to carcinogenesis and it also exerted inhibitory effects on tumor initiation through activating transforming growth factor-beta (TGF-beta) signaling." (PMID 28659634, 2017). "All these results demonstrated that DACH1 might be an efficient tumor suppressor in lung adenocarcinoma tumor, which merits further investigation in the clinic." (PMID 26810067, 2016). "DACH1 also was found to repress bFGF-induced tumor initiation in glioma cells." (PMID 27203207, 2016). "In addition, various single oncogene (c-Myc, NeuT, H-Ras or v-Src) transformed prostate epithelial cells (PEC) reduced Dach1 expression both in cultured cells and in extirpated tumor tissues." (PMID 26682253, 2015). "Intriguingly, expression of DACH1 was strongly correlated with the tumor progression." (PMID 25940701, 2015). "The ectopic expression of DACH1 inhibits cellular proliferation in vitro and tumor growth in vivo." (PMID 25322986, 2014). "In this study, we examined whether epigenetic changes in DACH1 occurred in GCs and explored the role of DACH1 in tumour growth, invasion, metastasis and chemosensitivity in human GC." (PMID 24912879, 2014). "Since the high proliferation is a hallmarker of cancer cells and DACH1 was reported to inhibit tumor growth in vivo in a series of xenograft models, we examined PCNA expression, a surrogate marker of cellular proliferation, in a series of sections from the same sample." (PMID 25322986, 2014). "In addition, it appears that the tumour suppressor function of DACH1 can be moderated by the tissue microenvironment including the presence of growth factors, evidenced by tumorigenesis seen in cell lines grown in vitro in the presence of IGF-1." (PMID 24392136, 2014). "Further experimental study confirmed tumor suppresser function of DACH1 in lung and other cancers." (PMID 25477004, 2014). "The sequential epigenetic treatment with epigenetic modification agents decitabine/TSA induced DACH1 expression accompanied with decreased proliferation, providing a laboratory evidence to support the concept that inactivation of DACH1 contributed to tumor growth." (PMID 25322986, 2014). "DACH1 was regarded as a tumor suppressor or an oncogene in different kind of cancer." (PMID 24743895, 2014). "However, as a new tumor suppressor, detailed targets of DACH1 and its crosslinks with other oncogene/tumor suppressors remain to be further clarified." (PMID 25322986, 2014). "Thus the DACH1 expression was significantly reduced in cancer tissues, correlated inversely with the tumor grade and stage." (PMID 25322986, 2014). "Generally, DACH1 behaves as a tumor suppressor, and its expression is reduced in several cancers." (PMID 25322986, 2014). "Although these studies suggest DACH1 may function as a tumor suppressor, the molecular mechanisms remain poorly defined." (PMID 23798621, 2013). "Furthermore, DACH1 has been recognized as a tumor suppressor gene in humans." (PMID 38542074, 2024). "Further analysis proved that DACH1 inhibited the transcription of cyclin D1 and cyclin A by directly binding to its corresponding promoter region, thereby further repressing the proliferation of cells and tumor growth in various cancer types, such as BC and renal cancer." (PMID 36750914, 2023).
tumor (continued). "Therefore, metformin may play an anti-tumor role by reducing the accumulation of MDSCs in the TME through AMPK/DACH1/CXCL1 axis." (PMID 33027968, 2020). "Alternatively, reactivation of DACH1 expression could restrain tumor growth and metastasis." (PMID 27203207, 2016). "Moreover, the DACH1 protein level inversely correlated with tumor grade and TNM stage." (PMID 25322986, 2014). "Finally, we provide useful information on numerous TF genes whose roles in colorectal tumorigenesis have been relatively unexplored, such as DACH1, a development gene whose protein expression patterns in colorectal tissues raises interesting questions about its involvement in tumor growth." (PMID 24472434, 2014). "However, whether DACH1 is the key target of decitabine for in vivo tumor growth needs to be further evaluated." (PMID 25322986, 2014). "Several lines of evidence suggest DACH1 may function as a tumor suppressor." (PMID 23798621, 2013). "While Dachshund homolog 1 (DACH1) was recognized as a critical regulator in cancer progression, its role in promoting or suppressing tumor development remains a subject of ongoing debate." (PMID 40370966, 2025). "This study elucidates the critical roles of USP7 and DACH1 in CRC, revealing their involvement in tumor progression and potential as therapeutic targets." (PMID 40389405, 2025). "In this study, the roles of DACH1 and USP7 in CRC and their post-translational regulatory mechanisms were explored, revealing their significant roles in tumor development." (PMID 40389405, 2025). "MiR‐31 in turn facilitates β‐catenin stabilisation via directly repressing tumour suppressors CEBPA and DACH1, which direct the expression of multiple essential Wnt/β‐catenin pathway inhibitors." (PMID 38797942, 2024). "Metformin mediates the PMN-MDSCs reduction in the tumor via activation of AMPK, which upregulates dachshund homolog 1 (DACH1) expression on tumor cells and, therefore, downregulates CXCL1 expression." (PMID 37686159, 2023). "Second, HOTAIR down-regulates the expression of E-cadherin and miR-217, then activates the DACH1/JAK3/STAT3 and Wnt/β-catenin pathways, which are involved in the tumor’s EMT ability, which is important for primary tumor formation and metastasis." (PMID 36924407, 2023). "DACH1 indirectly activates E-cadherin via inhibiting the transcription of SNAI1 in BC, which suppresses tumor cell migration and invasion." (PMID 36750914, 2023). "Ectopic expression of DACH1 activated TGF-β signaling and inhibited cancer cell proliferation and tumor growth." (PMID 36750914, 2023). "In contrast, several factors assigned to the suppression of tumor cell migration and/or invasion as well as angiogenesis, such as DLC1, RHOU, DACH1, and RECK, were significantly downregulated in the brain-seeking cell line in comparison with the native one." (PMID 35163822, 2022). "DACH1 methylation leads to downregulation of TGF-β or decreased expression of Smad4, which is related to increased depth of invasion, late tumor stage, and poor differentiation." (PMID 34568328, 2021). "Metformin inhibits NF-κB expression by increasing AMPK phosphorylation and inducing Dachshund homologue 1 (DACH1) mRNA expression, thereby reducing MDSCs migration and inhibiting CXCL1 secretion in esophageal carcinoma cells and tumor xenografts." (PMID 33027968, 2020). "Human Dachshund homolog 1 (DACH1) is a key member of retinal determination gene network (RDGN), which regulated cell proliferation, apoptosis, tumor growth and progression." (PMID 31998654, 2019). "Our study proved that CXCL8 acted as an unfavorable factor promoting to tumor progression and poor prognosis of ADC, while DACH1 antagonized CXCL8 to provide a favorable survival of ADC patients." (PMID 29636079, 2018). "Immunohistochemistry analysis was conducted to assess the protein abundance of DACH1, CD44, Myc, Sox2, Fibronectin, Vimentin, EGFR, Ki-67 in nude mice xenograft tumor tissues with overexpression of DACH1 and the GFP controls." (PMID 28659634, 2017).